CDK4 (cyclin dependent kinase 4)
Diseases named in the same sentence as CDK4 in open-access papers (continued):
Sharing a sentence is not in itself a finding about the gene and the disease.
breast cancer (continued). "The inhibition of cell cycle regulators such as CDK4 and CDK6 has become a new therapeutic frontier for the treatment of breast cancer (BC)." (PMID 31506466, 2019). "ER plays a substantial role in the growth of breast cancer by regulation of cell cycle proteins, such as cyclinD1, E2F1, and c-myc, among others, and tumor cells resistant to CDK4/6i continue to rely on the ER pathway to drive tumor growth." (PMID 31852484, 2019). "Through prospective modeling HER2+ breast cancer using the classic MMTV-neu mouse model, we find that long-term efficacy of combined CDK4/6 and HER2-targeted therapy is diminished by acquisition of resistance." (PMID 31444334, 2019). "As inhibition of CDK4/6, a downstream target of ERK1/2, reportedly upregulated drug-induced autophagy in breast cancer, we investigated the effect of ERK inhibition on autophagy in PSCs." (PMID 31133044, 2019). "Further reported CASC9 target genes were CDK4, CyclinD1 (CCND1), E-Cadherin (CDH1) and BCL2 in lung adenocarcinoma, ESCC cells, oral squamous cell carcinoma and in breast cancer." (PMID 31412811, 2019). "Data from these studies demonstrate the potential for CDK4/6 inhibitor-based combinations as second-line therapies for patients with advanced HR+, HER2− breast cancer who have received prior single-agent endocrine therapy." (PMID 29164421, 2018). "The combined suppression of the CDK4/6 and PI3K/AKT/mTOR pathway already proved to be synergistic in cells derived from T-ALL, malignant pleural mesothelioma, and breast cancer." (PMID 30544932, 2018). "Limited data are available from trials of the CDK4/6 inhibitors palbociclib and abemaciclib, as well as fulvestrant, in patients with HR+/HER2− advanced breast cancer." (PMID 30340505, 2018). "Abemaciclib is a CDK4/6 inhibitor that has made it into phase III clinical studies and is even FDA-approved for certain advanced breast cancers." (PMID 30340359, 2018). "The combination of the AI letrozole and the CDK4/6 inhibitor palbociclib was studied in the phase II PALOMA-1 trial, which enrolled postmenopausal women with advanced ER-positive, HER2-negative breast cancer." (PMID 30564467, 2018). "A selective CDK4/6 inhibitor, palbociclib, became recently approved as first-line treatment for oestrogen-positive, HER2-negative breast cancer patients." (PMID 30662724, 2018). "In sum, these data show that dual inhibition of CDK4/6 with PB and ERα with BZA is an effective combination with significant activity against breast cancer cells expressing WT or constitutively active mutant ERα." (PMID 30489256, 2018). "Taken together, this data suggest that it is reasonable to combine HER2-targeted agents with synergistic combinations of CDK4/6 inhibitors and antihormonal agents for the treatment of patients with HR+/HER2+ breast cancer." (PMID 30018827, 2018). "CDK4/6 inhibitors represent a new treatment standard for hormone receptor-positive (HR+), HER2-negative advanced breast cancer (BC) patients." (PMID 30511015, 2018). "Recent data have also shown promising results for CDK4/6 inhibitor-based regimens in patients with HR+, HER2− breast cancer who received prior single-agent endocrine therapy." (PMID 29164421, 2018). "Multiple clinical trials are underway to test triple combinations of antihormonal therapy with HER2 and CDK4/6-targeted agents in locally advanced and metastatic HR+/HER2+ breast cancer, offering new hope to patients with this challenging disease." (PMID 30018827, 2018). "Cyclin D1, p-CDK4, and p-Rb exhibit a concerted upregulation in the LEM4 overexpressing ER+ breast cancer cells." (PMID 30301939, 2018). "Palbociclib is a clinically-approved inhibitor of CDK4 and 6 currently used for treating ER+HER2− breast cancers." (PMID 30111820, 2018).
breast cancer (continued). "However, a very recent study based on mouse models of breast cancer and other solid tumors and on a confirmatory trascriptomic analysis of serial biopsies from a clinical trial involving CDK4/6i in breast cancer, showed that CDK4/6 inhibition might also induce a broad spectrum of immunologic events." (PMID 30631751, 2018). "Certain subtypes of cancers such as ER positive, HER-2 positive breast cancer and KRAS induced lung cancer cells have been found to be particularly vulnerable to Cdk4/6 inhibition." (PMID 29789630, 2018). "Moreover, CDK4 is found to be highly expressed in aggressive tumors and its expression correlate with poor overall and relapse-free survival outcomes as well as poor prognostic features of breast cancer patients, suggesting a central role for this protein in cancer development and progression." (PMID 29063134, 2018). "In conclusion, we have recently seen significant improvements in PFS in selected breast cancer patients based on novel drug combinations involving AIs, mTOR inhibitors, HER2 directed therapies, PI3K inhibitors and CDK4/6 inhibitors." (PMID 27923036, 2017). "Together, the data show that abemaciclib is a CDK4 and CDK6 inhibitor that demonstrates both in vitro and in vivo antitumor activity in breast cancer models." (PMID 29050219, 2017). "Overall, our study demonstrates the importance of CDK4/6–DUB3 axis in regulating breast cancer metastasis and provides a rationale for potential therapeutic interventions in the treatment of breast cancer metastasis." (PMID 28067227, 2017). "We next studied the effect of CDK4/6 and GLS1 inhibitors alone and in constant ratio (1:4) combinations on the viability of HCT116 colorectal cancer and MCF‐7 and SK‐BR‐3 breast cancer cells (see also Table EV4)." (PMID 28978620, 2017). "As CAAT proteins are able to significantly stimulate breast cancer cell proliferation, we evaluated the effect of palbociclib, a selective CDK4/6-inhibitor, on CMCAAT enhanced proliferation of MCF-7, T47D and MDA MB 231 breast cancer cells." (PMID 28525384, 2017). "To interrogate the biological effect of downregulating these proteins, we knocked down CDK4 and/or CDK6 in two ER+ breast cancer cell lines, MCF7 and T47D via shRNA and siRNA." (PMID 28653662, 2017). "The expression level of CDK4, CD44, and CD24 was analyzed in 51 breast cancer cell lines containing mesenchymal-like (basal-B) and epithelial-like (basal-A and luminal) phenotypes." (PMID 27759034, 2016). "In summary, our data showed that miR-124 inhibited cell proliferation by CDK4 and MALAT1 induced cell proliferation by decreasing miR-124 in breast cancer." (PMID 26918449, 2016). "Furthermore we wanted to know whether MALAT1 increased CDK4 expression in breast cancer." (PMID 26918449, 2016). "In the same patient subgroup as the FALCON trial (postmenopausal HR+ advanced breast cancer), patients in MONALEESA2 who received ribociclib, a CDK4/6 inhibitor, experienced a 44% improvement in PFS, meeting its primary end point early." (PMID 28105074, 2016). "Importantly, by combining both elements of CDK4/6 response, it is possible to parse the current proliferative/non-proliferative subtypes into additional prognostic groups that could have significance in assessing risk of recurrence in ER+/HER2- breast cancer." (PMID 27564114, 2016). "The pharmacological blockade and siRNA-mediated silencing of KCa1.1 induced cell-cycle arrest in the G0/G1 phase through the down-regulation of cyclin-D1 and cyclin-dependent kinase 4 (CDK4) and attenuated breast cancer invasion and metastasis." (PMID 27973439, 2016). "CDK4/6 inhibitors like palbociclib enlarge the treatment armamentarium for ER-positive, HER2-negative breast cancer." (PMID 27429659, 2016). "However, the relationship between CDK4 and clinical prognosis for breast cancer remains unclear." (PMID 27759034, 2016).
breast cancer (continued). "CDK4 activity is crucial for proliferation and development of the murine mammary gland and formation of HER2/neu driven mammary tumors." (PMID 26460486, 2015). "Our data showed that Nar differentially downregulated the expression of Cdk4, Cdk6, and Cdk7 in the human colorectal cancer cell lines SW1116 and SW837 and in the human breast cancer cell lines HTB26 and HTB132." (PMID 26074733, 2015). "In human breast cancer cells, simultaneous knockdown of Rb and FZR1 synergistically bypasses cell division arrest induced by the CDK4/6-specific inhibitor PD-0332991." (PMID 25562820, 2015). "This has been first demonstrated for cyclin D1 and CDK4/6 that are required for development of RAS- and HER2-driven mammary tumors and KRAS-induced lung tumors." (PMID 26295265, 2015). "Comparison of copy number analysis of HMEC, SUM149PT, SUM1315MO2 adherent cells revealed high copy numbers of AKT1, AURKA, CDK4, EGFR1, PAK1 and MYC in breast cancer cells as compared to HMEC cells." (PMID 26608463, 2015). "Of note, a combined cdk4/cdk6 inhibitor, palbociclib, recently received “breakthrough therapy” status for the treatment of ER+/HER2- breast cancer." (PMID 26029996, 2015). "SPA treatment also caused a significant reduction in EGF-induced cell cycle progression, which was accompanied by the reduced expression of cyclin D1 and CDK4 and a corresponding increase in p21 and p27 levels in MDA-MB-231 breast cancer cells." (PMID 24736807, 2014). "We found that expression levels of the known cell cycle-regulating miR-34 targets CCND1, CDK4 and CDK6, were downregulated upon miR-34c expression in breast cancer cell lines." (PMID 25064703, 2014). "We then inhibited CDKs including CDK4/6, CDK2 and CDK1 individually using either RNAi or small molecule inhibitors, and compared sensitivity to CDK inhibition with MYC dependence in breast cancer cells." (PMID 24444383, 2014). "There are studies suggesting association between Her2 over-expression and CA in breast tumors, and one showing that mammary tumors in MMTV-Neu mice display CA, but the molecular contribution of Cdk2 and Cdk4 to Her2/Neu-mediated CA has yet to be elucidated." (PMID 23776583, 2013). "We identified many known drivers of breast cancer and other types of cancer, in the female dataset (e.g. GATA3, CCNE1, GRB7, CDK4)." (PMID 24194916, 2013). "It is thought that the ability of cyclin D1 to activate CDK4 is critical for driving tumorigenesis, and that CDK4-associated kinase activity is required to maintain this tumorigenesis, as shown in mice with Her2-induced, but not Wnt-1-induced and Ras-induced breast cancer." (PMID 23336272, 2013). "Because the breast cancer cell lines overexpressed cyclin D1, and cyclin A protein levels were elevated following irradiation, we tested whether knockdowns of their respective kinase partners CDK4 and CDK2 might alter the relative radioresistance of various breast cancer cell lines." (PMID 23886499, 2013). "Many known drivers of breast cancer, including GATA3, CCNE1, CDK4 and GRB7, as well as known drivers for other tumor types were identified among the FBC candidate drivers." (PMID 24194916, 2013). "Rather, we propose that a dual treatment strategy targeting CCND1/CDK4 and CCND1/CDK2 complexes will be necessary to effectively treat luminal breast cancers arising from elevated CCND1." (PMID 23390492, 2013). "CDK4/6 inhibitors, first-line treatments for advanced HR + /HER2- breast cancer, not only suppress tumor proliferation but may also reshape the immune microenvironment, offering new opportunities for immunotherapy." (PMID 41986650, 2026). "Cyclin-dependent kinases 4 and 6 (CDK4/6) play a central role in the regulation of cell cycle progression and represent important therapeutic targets in hormone receptor-positive, human epidermal growth factor receptor 2-negative (HR+/HER2-) breast cancer." (PMID 42075865, 2026).
breast cancer (continued). "Importantly, some of these pathways are already being targeted by FDA-approved therapies in breast cancer, such as PI3K inhibitors and CDK4/6 inhibitors." (PMID 41496977, 2026). "Therefore, in pretreatment samples, c-Myc expression levels, rather than Rb levels, inversely correlate with the therapeutic efficacy of combined CDK4/6 inhibitors and endocrine therapy as a first-line treatment in HR+/HER2− breast cancer." (PMID 39930131, 2025). "EMERALD enrolled participants with ER-positive/HER2-negative advanced breast cancer who had received one to two prior lines of endocrine therapy, mandatory pretreatment with a CDK4/6 inhibitor, and no more than one line of chemotherapy." (PMID 41226406, 2025). "Additionally, for advanced breast cancer patients with PIK3CA, AKT1, or PTEN alterations who have previously received CDK4/6i, capivasertib in combination with fulvestrant presents a viable treatment option." (PMID 40206206, 2025). "While CDK4/6 inhibitors have been effectively combined with ICI for the treatment of breast cancer, this combination with or without CDK2 inhibition has not yet been demonstrated to be clinically effective for metastatic melanoma." (PMID 40904502, 2025). "In addition, CDK4/6 inhibition has been reported to increase MHC class II molecules and induce new antigen ligands on HR+ breast cancer cells, further improving immune visibility." (PMID 39930131, 2025). "CDK4/6 inhibitors (CDK4/6i) in combination with endocrine therapy (ET) represent the therapeutic mainstay for patients with hormone receptor-positive, HER2-negative advanced breast cancer (HR + /HER2-ABC)." (PMID 39373732, 2025). "Interestingly, a recent study showed that CDK4/6 inhibitors blocked SLC7A11 expression by inhibiting SP1 binding to the SLC7A11 promoter and induced ferroptosis in luminal A breast cancer cells." (PMID 39833180, 2025). "Notably, AKT1, ERBB2 (HER2), CDK4, and CCNE1 are significantly amplified in tumor samples while PIK3CA displays the lower expression level in breast cancer." (PMID 40725120, 2025). "Cyclin-dependent kinase 4 and 6 (CDK4/6) inhibitors have emerged as a cornerstone of treatment for hormone receptor-positive (HR+), human epidermal growth factor receptor 2-negative (HER2−) advanced breast cancer." (PMID 39851968, 2025). "The trial included patients with HR+ breast cancer that recurred or progressed during or after aromatase inhibitor therapy, but included patients who had received these with or without a CDK4/6 inhibitor." (PMID 41226406, 2025). "A study found that administering abemaciclib, which is a CDK4/6 inhibitor in the early stage of HR-positive/HER2-negative (HR+/HER2−) breast cancer, rather than waiting until patients develop metastatic disease, was a cost-effective treatment strategy." (PMID 41008856, 2025). "The commercially available and FDA-approved CDK4/6 inhibitors Palbociclib, Ribociclib, and Abemaciclib have different inhibition profiles against CDK isoforms resulting in diverse phenotypic effects on ER+ breast cancer." (PMID 40736275, 2025). "In breast cancer, vascular endothelial growth factor (VEGF) and hypoxia inducible factor (HIF)-1 are elevated in hypoxic environments, which attenuates the effects of CDK4/6 inhibitors." (PMID 38965074, 2025). "Ribociclib followed as the second CDK4/6 inhibitor approved in 2017, and abemaciclib was the third FDA-approved CDK4/6 inhibitor, indicated for use with aromatase inhibitors or fulvestrant in treating advanced or metastatic HR-positive/HER2-negative breast cancer." (PMID 40861456, 2025). "Next, a recent trial has shown a correlation between macrophage abundance and cyclin E levels in metastatic ER-positive/HER2-negative breast cancer patients, suggesting that the immune TME may be useful in predicting CDK4/6 inhibitor efficacy." (PMID 41388212, 2025).
breast cancer (continued). "CDK4/6 inhibitors block Rb phosphorylation, induce G1 arrest, and suppress tumor proliferation, forming the mechanistic rationale for their use in HR+/HER2− breast cancer." (PMID 41551151, 2025). "Thus, ER+ breast cancer cells refractory to palbociclib can be regulated in the in vitro and in vivo experimental models; this may explain why some ER+ breast cancer subjects who progress during a specific CDK4/6i then might become sensitive to another CDK4/6i." (PMID 40244377, 2025). "Importantly, in vitro we treated organoids with the CDK4/6 inhibitor palbociclib, an FDA-approved small molecule inhibitor used to treat estrogen receptor positive (ER+) breast cancer." (PMID 40562540, 2025). "When combined with endocrine therapy (ET), CDK4/6i enhance the effectiveness of ET and improves outcomes in hormone receptor-positive (HR+)/human epidermal growth factor receptor II-negative (HER2 −) breast cancer." (PMID 40377782, 2025). "The three CDK4/6is approved for use in clinical practice for first-line treatment of advanced estrogen receptor-positive, HER2-negative breast cancer together with endocrine therapy (palbociclib, ribociclib, and abemaciclib) are associated with an increase in progression-free survival." (PMID 40361493, 2025). "Similarly, in CDK4-addicted HR + /HER2- breast cancer models (MCF7 and CAMA1), the impact on cell cycle proteins following CDK4 depletion was more pronounced than CDK2 depletion." (PMID 39924553, 2025). "Despite the introduction of many molecules targeting HER family of receptors, CDK4 and 6, PDL1, poly (ADP-ribose) polymerase (PARP), and PI3K/AKT pathway in breast cancer therapy, chemotherapy remains the first line of treatment in breast cancer treatment." (PMID 40573259, 2025). "The CDK4/6 inhibitors (CDK4/6i) palbociclib, ribociclib, and abemaciclib have been approved by the FDA for the treatment of metastatic hormone receptor-positive (HR+) and human epidermal growth factor receptor 2-negative (HER2−) breast cancer." (PMID 39930269, 2025). "TIS was also observed in breast cancer, Ewing sarcoma, and neuroblastoma following treatment with CDK4/6 inhibitors 86, or in lung cancers and pancreatic cancers following treatment with MEK and CDK4/6 inhibitors 11, 87-90." (PMID 40860134, 2025). "While neoadjuvant endocrine therapy (NET), with or without a CDK4/6 inhibitor, is an established treatment option for estrogen receptor-positive breast cancers, optimal patient selection and second-line treatment for non-responders remain uncertain." (PMID 41496421, 2025). "The sequential radiotherapy and a CDK4/6 inhibitor plus ET were effective and well-tolerated, which could serve as a feasible option for neoadjuvant therapy for HR-positive, HER2-negative breast cancers." (PMID 40719174, 2025). "Some innovative drugs (antibody drug conjugates, CDK4/6 inhibitors, PARP inhibitors, selective estrogen degraders, and immune checkpoint inhibitors) have allowed for considerable improvements in outcomes for patients with breast cancer of all subtypes." (PMID 40940865, 2025). "Preclinical studies suggest that CDK4/6 inhibitors can inhibit Treg cell proliferation and upregulate MHC molecule expression on tumor cells, potentially enhancing anti-tumor immunity in breast cancer." (PMID 39930131, 2025). "Background and Objectives: CDK4/6 inhibitors (CDK4/6i) have revolutionized the treatment of hormone receptor-positive HER2 negative (HR(+)/HER2(-)) breast cancer." (PMID 40142360, 2025).